C20orf144 (chromosome 20 open reading frame 144)
Synonyms: Bclt; dJ63M2.6
Tractability: No criterion of Open Targets' tractability assessment is met for any kind of drug.
Gene: Protein-coding gene on chromosome 20 (33,662,327 to 33,665,619, forward strand). Ensembl gene ENSG00000149609.
Genetic constraint (gnomAD): Loss-of-function variants: 9 observed, 3.81 expected, observed/expected ratio (o/e) 2.36. That is too few expected variants to judge how well the gene tolerates losing a copy. Missense variants: 289 observed, 185.8 expected, observed/expected ratio (o/e) 1.56, 90% interval 1.41 to 1.72. Synonymous variants: 126 observed, 83.75 expected, observed/expected ratio (o/e) 1.5, 90% interval 1.3 to 1.74.
Homologues: Orthologues: chimpanzee C20H20orf144 (98% identical), macaque C10H20orf144 (87% identical), mouse 1700003F12Rik (54% identical), rat C3h20orf144 (54% identical).